SP1 (Sp1 transcription factor)
Diseases named in the same sentence as SP1 in open-access papers (continued):
Sharing a sentence is not in itself a finding about the gene and the disease.
cancer (continued). "Sp1 acts as a repressor of TERT in cancer cells by forming a complex with Sp3, while in Kaposi sarcoma associated herpes virus (KSHV), Sp1 becomes an activator via interactions with latency-associated antigen—briefly known as LANA." (PMID 34440361, 2021). "Sp1 represents an essential promoter in cancer cells and plays an important role as a basal transcription factor." (PMID 34531430, 2021). "As overexpression of SP1 occurs in many cancers, it is likely that SP1 overexpression makes an important contribution to the increased C1GalT1 expression in cancer." (PMID 34944925, 2021). "Sp1 is a highly regulated transcription factor involved in regulating a large number of genes that contribute to the “hallmarks of cancer”." (PMID 33484377, 2021). "SP1 is an essential transcription factor for gene regulation and can drive the expression of many cancer-related genes." (PMID 34452648, 2021). "SP1 level affects tumor stage and differentiation, which implies an unfavorable prognosis in these cancers." (PMID 34257529, 2021). "An example target gene CDC6 (a cell-cycle regulator) shows promoter binding of SP1 at these motifs by ChIP-Seq in cancer cells." (PMID 33931649, 2021). "Upregulation of Sp1 expression is a poor prognostic factor in multiple cancer types, including gastric, pancreatic, and lung." (PMID 33445667, 2021). "Previous studies reported that Sp1 expression correlated with dismal patient outcome in various cancer types, including CSCC." (PMID 33484377, 2021). "In fact, previous studies have demonstrated that SP1 activated or repressed transcription of multiple miRNAs in cancer." (PMID 33731131, 2021). "In cancer cells, Sp1 promotes fat production by up‐regulating the expression of sterol regulatory element binding protein‐1c (srebp‐1c) and FASN." (PMID 33369233, 2021). "The results of this study support the anticancer efficacy of PCC-1, which regulates Sp1 in human cancer cells, for clinical application." (PMID 34531430, 2021). "The relationship between expression of SP1 and clinicopathological behaviors and prognosis of solid cancers has been addressed in many studies, so we decided to carry out this meta-analysis to evaluate the carcinogenic role of SP1 in cancers." (PMID 34257529, 2021). "In all, carcinoma tissues tended to have elevated SP1 expression, which is related to clinicopathological characteristics of tumors, implying the central role of SP1 in tumor progression." (PMID 34257529, 2021). "According to a few studies, BA inhibits the growth of cancer cells by stimulating proteasome-dependent downregulation of Sp1, Sp3, and Sp4." (PMID 32050495, 2020). "The transcription activity of Sp1 in cancer cells is enhanced by various oncogenes like Ras, Src, and Raf, especially through the p42/p44 mitogen-activated protein kinase/extracellular signal-regulated kinase (MAPK/ERK) pathway." (PMID 32050495, 2020). "Since EGFR expression is regulated by multiple factors, including specific protein (Sp) transcioption factors through interaction with HDAC1 and HDCA2 in cancer cells 19, 20, we tested the effect of Sp1 and Sp3 knockdown on EGFR activity and HDCA expressions." (PMID 32226300, 2020). "In this review, we address the structure, function, and biology of Sp1 in normal and cancer cells, underpinning the involvement of Sp1 in OC tumorigenesis." (PMID 32050495, 2020). "It is well established that Sp1 interacts with c-JUN in several cancers, and c-JUN acts synergistically with Sp1 to activate downstream oncogenes." (PMID 33230457, 2020). "It is well documented that Sp1 is over-expressed in many cancers, including lung, breast, gastric and colorectal cancers." (PMID 33329003, 2020). "Overexpression of transcription factors YY1, HSF1 and SP1, known to regulate Ub gene expression, is a predictor of poor prognosis and shorter survival in several cancers." (PMID 32751694, 2020).
cancer (continued). "An antipsychotic drug, penfluridol, is currently used as an anti-cancer drug since it can downregulate the TFs like Sp1, Sp3, and Sp4." (PMID 32050495, 2020). "It is also found that Sp1 supports angiogenesis and opposes apoptosis in cancer cells, thereby aggravating tumorigenesis." (PMID 32050495, 2020). "Increasing evidence has also shown that Sp1 and Sp3 are expressed at higher levels in a number of cancer cells than in normal cells, and knockdown of Sp1 or Sp3 in cancer cells dramatically reduced tumorigenic and metastatic phenotypes." (PMID 32641483, 2020). "When SP1 is overexpressed and contributes to the malignant phenotype of a variety of human cancers by upregulating genes that enhance proliferation, invasion, and metastasis as well as stem-ness and chemoresistance." (PMID 32050495, 2020). "Taking an example for SP1, SP1 was considered as a cancer gene only by MinNetRank and was ranked 3rd, 3rd, 3rd, 2nd, 3rd,and 1st in TCGA-LIHC, LIRI-LIHC, TCGA-STAD, TCGA-BLCA, TCGA-LUAD, and TCGA-SKCM, respectively." (PMID 33488678, 2020). "Betulinic acid (BA) is an anti-cancer drug that can inhibit topoisomerase and has also been used for downregulation of Sp1 expression and its regulated pro-oncogenes in various cancer cells." (PMID 32050495, 2020). "The metabolism in cancer cells is mainly controlled by the PI3K/AKT pathway by Sp1-mediated transactivation of various oncogenes." (PMID 32050495, 2020). "Until now, very few drug compounds or natural extracts have been used to specifically target Sp1 for treating various cancer forms." (PMID 32050495, 2020). "Immunostaining of candidate proteins MAX, TCF7L2, YY1, IRF1, STAT6, SP1, and E2F1 (selected based on qPCR results and/or associations to cancer in general) was performed in additional FTC specimens as outlined in the “Materials and Methods” section." (PMID 33063251, 2020). "Some miRNAs over expressed in cancer, such as members of the miR-17-92 (miR-20a/miR-17-5p) and miR-27a clusters indirectly maintain high expression of Sp1, Sp3 and Sp4." (PMID 32050628, 2020). "Previous studies have shown that the high expression of SP1 is correlated with aggressive behavior in many types of cancers and decreased survival rate of the patients." (PMID 32977589, 2020). "Another interesting feature of the LOX family interactome is the over-representation in the network of the transcription factor SP1, which is over-expressed in many cancers in keeping with the role played by LOX and LOXLs in these diseases." (PMID 33383846, 2020). "SP1 was recently shown to promote tumour growth by inhibiting apoptosis and conferring chemo- and radiation resistance to cancer cells." (PMID 32046773, 2020). "Much like SK1, higher levels of Sp1 in these cancers are correlated with increased severity, stage, angiogenesis, and metastasis." (PMID 33171624, 2020). "Targeting Sp1 TF directly with the help of Mir-128 and Mir-377 reduces the rate of cell cycle, proliferation, and invasion of the cancer cells." (PMID 32050495, 2020). "It was found that penfluridol inhibits cancer cell growth by suppressing expressions of α6- and β4-integrins, primarily regulated by the Sp1 along with orphan nuclear receptor 4A1 (NR4A1)." (PMID 32050495, 2020). "In many type of cancer tissue, SP1-mediated transcriptional activated is enhanced, which leads to tumorigenesis, progression and metastasis." (PMID 31101117, 2019). "It was proposed that FXR induced phosphorylation of SP1 (Sp1 transcription factor) and by this promoted cancer progression." (PMID 31379749, 2019). "Ajuba is a newly defined transcriptional co-regulator and plays important role in various cancer development, while SP1 is a classic transcription factor, and is closely related with a variety of gene expression and cancer development including PDAC." (PMID 31101117, 2019). "Our data suggest that NAB2 upregulation facilitates EGF-mediated cancer cell invasion through the transactivation of Sp1-dependent tumor-promoting genes." (PMID 30845713, 2019).
cancer (continued). "SP1 is a highly regulated transcription factor that plays a critical role for the regulation of genes involved in cancer progression." (PMID 30976063, 2019). "In this study, we found that Sp1-dependent TMBIM6 overexpressing cells are less sensitive against paclitaxel and cyclophosphamide treatment, indicating a role of Sp1-dependent TMBIM6 expression in the cancer cells resistance to stress." (PMID 31336725, 2019). "Existing evidences report that several key transcription factors contribute to the up-regulation of lncRNA in human cancers, such as SP1, ELK1, STAT3 and YY1." (PMID 31713587, 2019). "All of this evidence supports our observation of higher levels of nuclear Sp1 in PMA treated and PKCε and PKCι overexpressing cells, leading to the possible enhanced induction of TMBIM6 gene in cancer by Sp1 in PKC dependent manner." (PMID 31336725, 2019). "Sp1 is a ubiquitous transcription factor that is involved in cell proliferation and cancer development." (PMID 30818757, 2019). "Our data suggest that upregulation of NAB2, a corepressor of EGR1, permits EGF-mediated cancer invasion during conditions of EGR1 overexpression through the transactivation of Sp1-dependent tumor-promoting genes." (PMID 30845713, 2019). "Further analysis of the correlation between SP1 mRNA and hsa-miR-149-5p in cancer tissues and adjacent normal tissues showed that SP1 mRNA and hsa-miR-149-5p were negatively correlated (r = −0.81, −0.77)." (PMID 31270251, 2019). "Results showed higher viable cells in P9-TMBIM6-HA transfected cells compared to P9-(mSp1d, mSp1p)-TMBIM6-HA cells, indicating the Sp1-dependent TMBIM6 expression role in the cancer cell protection against stress." (PMID 31336725, 2019). "In this study, we report that TMPRSS4 upregulates bcl-2 and survivin to enhance cancer cell survival, and inhibits anoikis and drug treatment sensitivity, potentially via upregulation of AP-1, Sp1, and NF-κB." (PMID 31292507, 2019). "It has been shown that the G-allele of SNP309 increased the affinity of the transcription factor Sp1 to the MDM2 P2 promoter, leading to elevated MDM2 expression and increased cancer risk." (PMID 30956778, 2019). "SP1 was overexpressed in a variety of human cancers and regulated the expression of genes involved in cell proliferation, differentiation, apoptosis, and angiogenesis." (PMID 29654167, 2018). "Previously, we showed that ZEB2 cooperates with the transcription factor Sp1 to function as a transcriptional activator of vimentin, integrin α5, and cadherin-11, which promotes cancer cell invasion." (PMID 29416649, 2018). "As a transcription factor, to understand the role of SP1 in cancers, the function of the downstream targets of SP1 deserves further investigation." (PMID 29654167, 2018). "Terameprocol, a semisynthetic derivative of a naturally occurring plant lignin, downregulates Sp1-mediated transcription of survivin to promote cancer cell apoptosis." (PMID 29416649, 2018). "In this study, we found that ZEB2 upregulated survivin, cyclin D1, and vascular endothelial growth factor (VEGF) through cooperation with Sp1 to promote cancer cell survival and proliferation and endothelial cell activation." (PMID 29416649, 2018). "Since SP1 plays critical roles in diverse biological contexts, such as neurodegeneration and cancer, MitA has been extensively used in diseases in which abnormal SP1 expression or activation is present." (PMID 29747385, 2018). "A recent report showed that MALAT-1 is an Sp1-regulated gene and we therefore determined if ROS-inducing anticancer agents that downregulate Sp1, Sp3 and Sp4 in pancreatic and other cancer cell lines also decrease MALAT-1 expression." (PMID 29389953, 2018).
cancer (continued). "The present study demonstrates that ZEB2 induces expression of Sp1-regulated genes such as survivin, bcl-2, cyclin D1, and VEGF by cooperating with Sp1 to promote cancer cell survival and endothelial cell activation directly during metastasis." (PMID 29416649, 2018). "Amongst these targets of SP1, the phosphatase and tension homolog deleted on chromosome ten (PTEN) is a well-established tumor suppressor, which is down-regulated or mutated in cancers and contributes to the initiation and development of cancers." (PMID 29654167, 2018). "Overexpression of SP1 has been found in a variety of cancers and was correlated with the worse prognosis of the cancer patients." (PMID 29654167, 2018). "Overexpressed Sp1 differentially regulated a large number of genes which promoted cancer development, angiogenesis and metastasis." (PMID 29653560, 2018). "Sp1 regulates the expression of many genes involved in various cellular functions such as differentiation, proliferation and apoptosis in cancer cells." (PMID 29751546, 2018). "After the analysis of TCGA HCC database, we observed that Bak transcription in cancer tissue was higher than that in non-cancer tissues, and its transcription was correlated with Sp1 and Sp3 transcription level." (PMID 29653560, 2018). "Recent studies reported that the expression and activity of SP1 were regulated by miRNAs and affected the cancer progression." (PMID 29654167, 2018). "Previous studies demonstrated that SP1 promoted the cancer cell migration and proliferation via inhibiting PTEN." (PMID 29654167, 2018). "A coordinative binding of HIF-1 and SP1 transcription factors is necessary for CA9 expression in oxygenated cancer cells, and lactate augments the level of expression by increasing HIF-1α availability." (PMID 29100428, 2017). "Taken together, these observations indicated that SP1 is crucial for TGF‐β mediated up‐regulation of NKG2DLs in cancer cells." (PMID 28165192, 2017). "The experiment was performed in human Hela cells and the study focused on finding novel Sp1 targets involved in proliferation and cancer." (PMID 28466020, 2017). "TIP60-dependent acetylation of Sp1 provides a window for therapeutic intervention in cancers driven by Sp1 overexpression." (PMID 29045464, 2017). "Decrease in Sp1 protein expression by TA treatment has been demonstrated in several cancer models, both in vitro and in vivo." (PMID 28099934, 2017). "Mithramycin A was shown to inhibit the growth of various cancers (including CC) by decreasing Sp1 protein." (PMID 29073938, 2017). "These motifs were similar to motifs of the TFs MAZ, the CAC-binding protein, and SP1, which were discovered in at least three of the five cancer types." (PMID 28684851, 2017). "Based on these results, we concluded that Nm23-H1-mediated Sp1 expression negatively regulates cancer cell migration in vitro and in vivo." (PMID 28831131, 2017). "Accordingly, in order to design drugs effective at inhibiting Sp1 expression for use in cancer therapies, the various molecular pathways that contribute to Sp1 expression need to be considered." (PMID 28831131, 2017). "Owing to its binding sites present in a large number of genes, downregulation of Sp1 is likely to have a profound effect on cancer cell survival." (PMID 28484232, 2017). "Our present work revealed that overexpression of SP1 not only has the effect on malignant tumour, but also plays an important role in regulation of NKG2DLs expressed on tumour cells." (PMID 28165192, 2017).
cancer (continued). "A recent study also demonstrated that an IRES-motif localized within the 5′UTR of Sp1 mRNA was involved in Sp1 expression during cancer formation." (PMID 28831131, 2017). "There are several TFs, such as EGF1, HIF1A, the E2F family and NANOG, that play different regulatory roles in tumor cells, and it is also known that SP1 expression levels are higher in cancer cell lines than in normal cells." (PMID 28531296, 2017). "By regulating the expression of effector molecules including SREBP-1c, VEGF, MMP2, Sp1 plays pivotal roles in cancer cell metabolism, proliferation, and metastasis." (PMID 29262634, 2017). "It is evident, therefore, based on previous studies and the study presented here, that multiple strategies have been developed by cells to control Sp1 expression during cancer progression." (PMID 28831131, 2017). "Sp1 is a ubiquitously expressed transcription factors that function extensively in cancer initiation and progression by binding to GC/GT boxes of target gene promoters to enhance transcription." (PMID 28352075, 2017). "β-catenin is an important transcription factor involved in cell adhesion; however, Sp1 plays an important role as a basal transcription factor and represents an essential promoter in cancer cells." (PMID 28225083, 2017). "After that, we investigated Sp1 expression after FXR deletion in the cancer cell lines so as to reveal their correlation." (PMID 28402278, 2017). "Compared to its expression in normal tissues and cells, the expression of Sp1 is higher in cells and tissues in different cancer types." (PMID 28831131, 2017). "Of note, we showed a positive correlation between PLD1 and Sp1 expression in the cancer tissues (r = 0.357; p < 0.001)." (PMID 29088790, 2017). "Sp1 is tightly regulated in the early and late stages of tumorigenesis to influence cancer progression." (PMID 28831131, 2017). "A common abnormality of PDAC is overexpression of specificity protein-1 (Sp1), which was said to correlate with malignant phenotypes of human cancers." (PMID 28352075, 2017). "The current study identified Sp1 and Grp78 as potential targets for future therapeutics in PDAC; discovered a protective role of Sp1 in cancer; as well as further detailed ER stress response in cell death mechanisms." (PMID 28484232, 2017). "SP-1 was also reported to promote invasion and migration of cancer cells by upregulating expression of the metastasis-associated proteins integrin α5 and cadherin-11." (PMID 28286419, 2017). "As a transcriptional factor, Sp1 can regulate many genes expression to promote the progression and poor prognosis of many cancers." (PMID 29262634, 2017). "Kumar and colleagues described increased expression and activity of Sp1 in epithelial carcinoma in comparison to benign tumors." (PMID 28774282, 2017). "In both clinical specimens and cancer models, previous studies have revealed that Sp1 levels correlate with stage, invasive potential, metastasis, and even patient survival." (PMID 26763486, 2016). "Studies in cancer cell lines show that Sp1, Sp3 and Sp4 are highly expressed, and RNA interference (RNAi) studies indicate that Sp transcription factors regulate genes associated with cell proliferation, survival and migration/invasion [reviewed in 14]." (PMID 26967243, 2016). "Abnormal interaction between ZBTB10 and Sp1 is seen in several different cancer cell lines, with ZBTB10 consistently exhibiting tumour-suppressing activity." (PMID 27539887, 2016). "This also explains the observation that c-Myc and Sp1 expression correlates with hTERT transcription in various cancer cell lines." (PMID 27548225, 2016).